TAGLN (transgelin)
Diseases named in the same sentence as TAGLN in open-access papers (continued):
Sharing a sentence is not in itself a finding about the gene and the disease.
bladder cancer (continued). "Overall, Alterations in the expression of VCL, FLNA, TAGLN, ACTA2, COL6A2, and CALD1 may play important roles in the development of bladder cancer, suggesting their potential value in early detection, molecular subtyping, and targeted therapy." (PMID 41181151, 2025). "Finally, six B-cell marker genes (VCL, FLNA, TAGLN, ACTA2, COL6A2, and CALD1) that were downregulated in bladder cancer were screened using the PPI network, survival curves, ROC curve analysis, and expression validation." (PMID 41181151, 2025). "By survival analysis, we found that their overall survival and disease-free survival curves also showed similarities, such as ACTA2 and TAGLN, FLNA and TPM1, suggesting that these genes have similar functions and are likely to be co-expressed and play a synergistic role in bladder cancer." (PMID 37274283, 2023). "The precise functions and the regulatory mechanisms of TAGLN in the bladder carcinoma cells are still not illustrated and explored." (PMID 31591355, 2019). "TGF-β1-stimulated migration and invasion of bladder cancer cells arise mediated by Src and FAK kinase as well as transgelin (TAGLN), an actin-binding protein that stimulates colony formation, migration, and invasion, as well as epithelial–mesenchymal transition." (PMID 31842336, 2019). "Transgelin (TAGLN/SM22-α) is a regulator of the actin cytoskeleton, affecting the survival, migration, and apoptosis of various cancer cells divergently; however, the roles of TAGLN in bladder carcinoma cells remain inconclusive." (PMID 31591355, 2019).
colon carcinoma (17 papers, 2010 to 2024). "The gradual loss of TAGLN function contributes to tumor progression and serves as a diagnostic marker in breast and colon cancer development." (PMID 39284282, 2024). "A prior study indicated that an early loss of TAGLN gene expression is important for tumor progression and viewed that as a diagnostic marker for breast and colon cancer development." (PMID 31591355, 2019). "Early study indicated that abolition of TAGLN expression is an important early event in tumor progression and a diagnostic marker for breast and colon cancer development." (PMID 31591355, 2019). "Hence, the loss of transgelin gene expression might be an essential step in the development of tumors and a diagnostic indicator for breast and colon cancer." (PMID 37834385, 2023). "In the present study, we found that both endogenous and exogenous transgelin were expressed in the cytoplasm and nucleus of the colon cancer cells." (PMID 32774160, 2020). "Findings from this study confirmed the localization of transgelin in the nucleus of the colon cancer cells." (PMID 32774160, 2020). "Manipulation of transgelin expression resulted in differential expression of a variety of genes and affected the biological behaviors of the colon cancer cells in vitro and in vivo." (PMID 32774160, 2020). "Over-expression of TAGLN affected the expression of 256 downstream transcripts and increased the metastatic potential of colon cancer cells in vitro and in vivo." (PMID 32774160, 2020). "This study aims to explore the mechanisms through which transgelin participates in the metastasis of colon cancer cells." (PMID 32774160, 2020). "The interaction between PARP1 and transgelin in human RKO colon cancer cells was further validated by immunoprecipitation and immunofluorescence assays." (PMID 32774160, 2020). "Immunofluorescence and immunoblotting analysis were used to determine the cellular localization of endogenous and exogenous transgelin in colon cancer cells." (PMID 32774160, 2020). "While the up-regulation of transgelin promoted the metastasis of colon cancer cells, down-regulation substantially decreased the ability of cell invasion and metastasis." (PMID 32774160, 2020). "The expression of transgelin in colon cancer cell lines (HCT116, SW480, RKO and LOVO) was detected by immunofluorescence and immunoblotting assays." (PMID 32774160, 2020). "The most downregulated gene was transgelin, an actin-binding protein that increases metastatic potential of colon cancer cells, followed by asparagine synthetase and the transcription factor E2F7." (PMID 28161520, 2017). "Overexpression of TAGLN protein has been observed in carcinomas of the stomach, liver, and esophagus, while decreased levels of TAGLN mRNA have been observed in breast and colon cancer cell lines and primary tumors." (PMID 23510049, 2013). "The regulatory effect of TAGLN on colon cancer progression needs to be further explored." (PMID 36523769, 2022). "Therefore, AEBP1, BGN, and TAGLN have been identified as potential biomarkers related to the response to FOLFIRI treatment of colon cancer." (PMID 36523769, 2022). "Herein, we verified the nuclear localization of transgelin in different colon cancer cell lines." (PMID 32774160, 2020). "Findings from our previous study showed that transgelin increased the metastatic potential of colon cancer cells by remodeling the cytoskeleton in the cytoplasm; it also altered the expression of metastasis-related genes, thereby promoting the formation of metastatic phenotypes in the tumor cells." (PMID 32774160, 2020). "Transgelin was found to localize in both the cytoplasm and nucleus of the colon cancer cells." (PMID 32774160, 2020). "In addition, RAS-dependent and RAS-independent downregulation of transgelin in human breast and colon carcinomas has been reported." (PMID 25109740, 2014).
colon carcinoma (continued). "Interestingly, genes that are associated with colon cancer progression (ANTXR1, EFEMP2, SULF1, TAGLN, VCAN, ZEB1 and ZEB2) were upregulated in patients co-overexpressing TAZ-AXL-CTGF." (PMID 23372686, 2013). "Since many actin-binding proteins have been proven to exert different biological functions in the cytoplasm and nucleus, we hypothesized that transgelin could play a central role in the invasion and metastasis of colon cancer cells through specific mechanisms in different cellular localization." (PMID 32774160, 2020). "Therefore, we speculate that transgelin may interact with other partner(s) to regulate the downstream target genes, thereby affecting colon cancer metastasis." (PMID 32774160, 2020). "Moreover, they have been implicated in the Rho GTPases activation pathway, which could be a major pathway for transgelin to participate in colon cancer metastasis." (PMID 32774160, 2020). "Transgelin binds poly ADP-ribose polymerase 1 (PARP1) and regulates the downstream Rho signaling pathway in the metastasis of colon cancer." (PMID 37363722, 2023). "However, the role of transgelin in colon cancer metastasis remains unknown." (PMID 32774160, 2020). "Although this study endeavors to delineate the mechanisms of how transgelin and PARP1 interaction influences the Rho signaling pathway and participates in colon cancer metastasis, a proper understanding of these mechanisms warrants more comprehensive analysis." (PMID 32774160, 2020). "Recent evidence suggests that transgelin/SM22 acts as a tumour suppressor with diminished expression in prostate, breast, and colon cancers." (PMID 37363722, 2023). "The role of TAGLN in CRC is vaguely describe, though one study showed that it could bind to PARP1 which involved in Rho signalling, therefore, inducing metastasis of colon cancer cells." (PMID 37476187, 2023). "In addition, the gene expression levels of AEBP1, BGN, and TAGLN were negatively correlated with OS and DFS in colon cancer patients." (PMID 36523769, 2022). "Thus, we examined the effect of exogenous TGFβ treatment on TAGLN expression, as well as on the expression of a number of TGFβ-responsive genes (ACTA2, and TPM1), in the RKO colon cancer cell model." (PMID 32393769, 2020). "Our results suggest that transgelin binds to PARP1 and regulates the expression of downstream key genes, which are mainly involved in the Rho signaling pathway, and thus participates in the metastasis of colon cancer." (PMID 32774160, 2020). "Therefore, we postulated loss of TAGLN during early stage and subsequent re-acquisition of TAGLN expression in late stages of COAD, suggesting a possible role for TAGLN in driving colon cancer progression." (PMID 32393769, 2020). "We found that IGFBP-rP1 could upreguate TAGLN, downregulate SOX9, IRS1, P15, AREG, IER5L, KRT8 in these colon cancer cells, indicating that these genes may be the important IGFBP-rP1 responsible genes in colon cancer." (PMID 20977730, 2010). "The upreguation of TAGLN and downregulation of SOX9, IRS1, P15, AREG, IER5L, KRT8 in RKO, SW620 and CW2 colon cancer cells indicated these genes may be the target molecules for the biological behaviour of IGFBP-rP1 in colon cancer." (PMID 20977730, 2010). "Our results support a hypothesis that transgelin interacts with PARP1 and regulates the expression of downstream key genes (CALM1, MYO1F, NCKIPSD, PLK4, RAC1, WAS and WIPF1), which are mainly involved in the Rho signaling pathway in the human RKO colon cancer cells." (PMID 32774160, 2020).
breast carcinoma (16 papers, 2008 to 2025). "Based on substantially high methylation frequencies in breast cancer, further studies focusing on TAGLN promoter methylation as a diagnostic marker, combined with other biomarkers, should seriously be considered." (PMID 26421063, 2015). "Kilin and transgelin were upregulated after 24 h of treatment and could be used as diagnostic and prognostic markers for breast cancer." (PMID 37834385, 2023). "Paeonol also inhibited breast cancer cell invasion by suppressing the signaling pathway of the gene encoding the Notch-1 one-way transmembrane receptor and reduced the expression level of transgelin two in MCF-7/PTX cells, thereby reversing the resistance of breast cancer cells to paclitaxel." (PMID 39588155, 2024). "TAGLN gene is frequently downregulated by DNA hypermethylation, and TAGLN promoter methylation profiles could serve as a future diagnostic biomarker, with possible clinical impact regarding the prognosis in breast cancer." (PMID 26421063, 2015). "TAGLN is differentially expressed among molecular breast cancer subtypes and predominantly upregulated in higher grade TNBCs45." (PMID 37709737, 2023). "Prognostic analysis of Transgelin in breast cancer, liver hepatocellular carcinoma, and sarcoma also showed that patients with high Transgelin expression had a long survival time." (PMID 34552870, 2021). "Both colorectal and breast cancer cells expressed a high level of TAGLN (22-kDa actin-binding protein)." (PMID 33919917, 2021). "In breast cancer, Transgelin affects the utilization of IL-8, which in turn affects tumor vascular mimicry (VM)." (PMID 34552870, 2021). "TAGLN expression was significantly and frequently downregulated via promoter DNA hypermethylation in breast cancer cells compared to NTB cells, and also in 13/21 (61.9 %) of breast tumors compared to matched normal tissues." (PMID 26421063, 2015). "Frequent hypermethylation of the TAGLN promoter region, in breast cancer even at low-grade tumors, is comparable to the hypermethylation frequencies of known TSGs in breast and other types of tumors." (PMID 26421063, 2015). "TAGLN methylation states also relate to the prognosis of breast cancer, as TAGLN promoter methylation levels were negatively correlated with cellular proliferation and worse prognosis marker ANLN expression in our tumor-normal matched tissue panel." (PMID 26421063, 2015). "Based on the high frequency of hypermethylation in breast cancer patients compared to healthy tissues, TAGLN promoter methylation levels can be used as an epigenetic based biomarker for diagnosis, either alone or together with other frequent markers." (PMID 26421063, 2015). "Here, we used the same technology and identified TAGLN as an important candidate biomarker, frequently downregulated by promoter hypermethylation in breast cancer." (PMID 26421063, 2015). "KM plotter, which uses public microarray expression data for survival analyses, was used to test the effect of TAGLN expression on OS or RFS of breast cancer patients." (PMID 26421063, 2015). "A closer look at the eight Ox-E/ER genes linked to these growth factors revealed that most (EGR1, PHLDA1, IGFBP5, TAGLN, DAB2, and FHL2) have been associated with breast cancer." (PMID 18631401, 2008). "Transgelin expression is decreased in lung and breast cancer." (PMID 34552870, 2021). "SM22/transgelin gene expression were down-regulated during a variety of cell types, as well as in several human cancers, including lung, renal and breast cancer." (PMID 27402083, 2016). "Here, we show that TAGLN is an epigenetically suppressed candidate epigenetic biomarker for diagnosis in breast cancer, by presenting its consistent downregulation of expression and frequent hypermethylation in breast carcinoma cell lines as well as in three independent breast tumor tissue cohorts." (PMID 26421063, 2015).
breast carcinoma (continued). "Our study is the first to document the regulation of TAGLN gene expression by promoter hypermethylation in both breast carcinoma cell lines and normal matched tumor breast tissues, as well as in tumor tissues of large set of publicly available data by means of bioinformatics analyses." (PMID 26421063, 2015). "These further studies with expanded breast cancer patient cohorts and bisulfite sequencing accompanied with expression analyses will determine whether TAGLN expression and/or methylation could also be used as a prognostic marker as well." (PMID 26421063, 2015). "In this study, we found that the expression of TAGLN was higher in grade 1 and 2 tumors compared to grade 3, suggesting that TAGLN expression could be decreased even more when the tumor progresses into a more undifferentiated state in breast cancer." (PMID 26421063, 2015). "Better survival of breast cancer patients with higher expression or lower promoter methylation of TAGLN, in addition to competence of its promoter methylation levels to discriminate cancer from healthy tissue, emphasize a possible clinical impact for this gene in breast cancer." (PMID 26421063, 2015). "And TAGLN, ASPN, KRT19 and MGST1 have important roles in the prognosis, invasion, metastasis and drug resistance of breast cancer." (PMID 37470685, 2023). "As another example, TAGLN was identified as a target of DNA hypermethylation in breast cancer by using microarray expression profiling of AZA- or DMSO-treated breast cancer and non-tumorigenic breast cells." (PMID 35568861, 2022). "Our novel findings support the essential role of TAGLN gene in breast cancer pathogenesis, regarding its negative effect on cellular proliferation and its consistent downregulation in tumors." (PMID 26421063, 2015). "TAGLN gene expression was analyzed with qRT-PCR and found to be significantly downregulated in 15 different breast carcinoma cell lines compared to the non-tumorigenic cell lines (P = 0.0034)." (PMID 26421063, 2015). "In this study, we utilized microarray expression profiling of AZA-treated breast cancer (BC) and non-tumorigenic breast (NTB) cell lines, and identified TAGLN gene to be a frequently hypermethylated gene and a potential future biomarker in breast cancer." (PMID 26421063, 2015). "NAMSs of the TAGLN probes were compared for different pathological features of breast cancer, and TAGLN methylation states were similar, independent of grade, Her2, and ER states, and sizes of the tumors." (PMID 26421063, 2015). "WalBC cells exhibited expression of known markers of basal invasive human breast cancers as well as increased KRT17, KRT 14 and KRT 19, DSP, s100A4, NDRG-1, ANXA1, TK1 and AQP3 gene expression and decreased gene expression of TIMP3, VIM and TAGLN." (PMID 18179684, 2008). "Using microarray expression profiling of AZA- or DMSO-treated breast cancer and non-tumorigenic breast (NTB) cells, we identified for the first time TAGLN gene as a target of DNA hypermethylation in breast cancer." (PMID 26421063, 2015).
atherosclerosis (14 papers, 2009 to 2025). A disease characterized by the build-up of fatty material and calcium deposition in the arterial wall resulting in partial or complete occlusion of the arterial lumen. "However, during early atherosclerosis, vSMCs undergo dedifferentiation whereby they lose canonical vSMC markers, such as α smooth muscle actin (αSMA) and transgelin (SM22), and reignite signaling pathways associated with development." (PMID 37200978, 2023). "Interestingly, TAGLN-deficient mice with an Apoe-KO background are reported to develop accelerated atherosclerosis compared with control Apoe-KO mice." (PMID 34902367, 2022). "Interestingly, transgelin, an actin-binding protein abundant in smooth muscle cells is downregulated in atherosclerosis and a deficiency accelerates atherosclerosis in apoE–/– mice." (PMID 22276189, 2012). "Lowered expression of TAGLN has also been observed in cardiovascular diseases, such as atherosclerosis (the atherosclerosis plaque), intracranial aneurysms, and aortic dissection." (PMID 37047799, 2023). "It is well known that the smooth muscle cell marker TAGLN (SM22α) is downregulated in the pathogenesis of atherosclerosis, restenosis, abdominal aortic aneurysm and other arterial diseases." (PMID 37421595, 2023). "On the other hand TAGLN has already been demonstrated to play a role in atherosclerosis." (PMID 22879930, 2012). "Phenotypic modulation of SMCs during human atherosclerosis is characterized by the downregulation of contractile SMC marker genes such as MYH11, TAGLN and CNN1, and activation of gene programs that promote vascular remodeling, lesion development and fibrous cap formation." (PMID 41107595, 2025). "We may think the VSMC phenotype change that reported in the atherosclerosis animal model is not the direct regulation of transgelin on VSMC but the role of the cytokines that holding true." (PMID 30338626, 2018).